YTHDF1 (YTH N6-methyladenosine RNA binding protein F1)
Diseases named in the same sentence as YTHDF1 in open-access papers (continued):
Sharing a sentence is not in itself a finding about the gene and the disease.
ovarian carcinoma (continued). "YTHDF1 was found to enhance the CSC-like characteristics of the cisplatin-resistant ovarian cancer cells by binding to m6A-modified TRIM29 mRNA and promoting its translation." (PMID 33928028, 2021). "In our previous study, we found that the m6A “reader” YTHDF1 aggravated ovarian cancer progression by enhancing EIF3C translation in an m6A-dependent manner." (PMID 34149801, 2021). "The public database of ovarian cancer and in vitro and in vivo experiments showed that the expression of YTHDF1 was related to the stage and prognosis of ovarian cancer." (PMID 33692959, 2021). "In our current study, according to the Kaplan–Meier plotter database, when YTHDF1, YTHDF2, WTAP, FTP, and ALKBH5 were highly expressed in ovarian cancer, they were validated as valuable prognostic risk factors for low OS and PFS with high HR." (PMID 33225598, 2021). "YTHDF1 amplification is common in ovarian cancer and its upregulation is related to poor prognosis." (PMID 39891297, 2025). "The m6A reader YTHDF1 promoted ovarian cancer progression via augmenting EIF3C translation." (PMID 38714753, 2024). "YTHDF1 is also abnormally high expressed in human ovarian cancer." (PMID 38343637, 2024). "In addition to ovarian cancer, YTHDF1 is overexpressed in cancer tissues and is correlated with poor prognosis." (PMID 36650570, 2023). "In ovarian cancer, YTHDF1 enhances the resistance of ovarian cancer cells to cisplatin, which may result from the maintenance of ovarian cancer CSCs through interaction with TRIM29." (PMID 37264402, 2023). "YTHDF1 and YTHDF2 are significantly expressed in ovarian cancer and may be associated with prognosis, while YTHDF3 may increase the pathological staging of ovaries." (PMID 37194218, 2023). "TRIM29 expression levels correlate with prognosis in OC and enhance CSC-like features in cisplatin-resistant OC cells; YTHDF1 promotes TRIM29 translation in an m6A-dependent manner which contributes to the stem cell-like phenotype in cisplatin-resistant ovarian cancer." (PMID 37194218, 2023). "YTHDF1 is overexpressed in ovarian cancer and knockdown of YTHDF1 inhibits tumor progression." (PMID 37474926, 2023). "Indeed, YTHDF1 is often amplified in ovarian cancer, and its up-regulation is related to poor prognosis." (PMID 35303965, 2022). "Recently, it was found that YTHDF1 regulates the translation of eIF3C via an m6A-dependent way, thus affects the global protein translation in OC, enhancing protein synthesis and promoting the tumorigenesis of ovarian cancer cells." (PMID 34794452, 2021). "However, the binding sites of ELF3C mRNA and YTHDF1 are mainly located in coding region and untranslated regions in ovarian cancer cells." (PMID 33692959, 2021). "Silence of YTHDF1 inhibited the growth and metastasis of ovarian cancer in vitro and in vivo." (PMID 33928028, 2021). "In ovarian cancer, YTHDF1 promotes tumor growth and metastasis." (PMID 33015074, 2020). "A recent study using multi-omics analysis reported that YTHDF1 promotes ovarian cancer occurrence and development through binding to m6A-modified EIF3C mRNA and consequently enhancing the EIF3C translation, which EIF3C is a subunit of the protein translation initiation factor EIF335." (PMID 32934298, 2020). "The m6A regulators RBM15, ZC3H13, YTHDF1, and IGF2BP1 may cause ovarian cancer immune infiltration." (PMID 37194218, 2023). "Thus, targeting YTHDF1 is expected to be a promising candidate for ovarian cancer therapy." (PMID 33928028, 2021). "YTHDF1 may have strong potential as a therapeutic target for ovarian cancer." (PMID 33928028, 2021). "YTHDF1 can also enhance the translation of EIF3C and augment overall translational output concomitantly, leading to tumorigenesis and metastasis of ovarian cancer." (PMID 40483535, 2025).
ovarian carcinoma (continued). "In the realm of ovarian cancer, YTH domain-containing family protein 1 (YTHDF1) is known to enhance the translation of eukaryotic translation initiation factor 3 subunit C, thereby driving tumorigenesis and metastasis." (PMID 38255219, 2024). "Encapsulation of YTHDF1 siRNA and docetaxel (DTX), a first-line chemotherapy drug for ovarian cancer, into MSC-derived MsEVs, resulted in significant tumor targeting and internal/lysosomal escape of YTHDF1 siRNA." (PMID 39062595, 2024). "YTHDF1 enhances EIF3C translation in an m6A‐dependent manner by binding to m6A‐modified EIF3C mRNA, thereby promoting tumorigenesis and metastasis in ovarian cancer." (PMID 39006762, 2024). "And through multi-omics studies, it is determined that its direct target in ovarian cancer cells is the translation initiation factor EIF3C, and YTHDF1 controls the translation of EIF3C in a m6A-dependent manner." (PMID 37005667, 2023). "YTHDF1 recognizes the target mRNA EIF3C in an m6A-dependent manner to facilitate its protein synthesis and plays an essential role in ovarian cancer growth and migration." (PMID 37194218, 2023). "According to the study, IGF2BP2, KIAA1429, and YTHDF1 regulators are highly amplified in OC, and the majority of m6A genes, including METTL3, KIAA1429, HNRNPC, ZC3H13, and IGF2BP2, are upregulated in ovarian cancer tissues." (PMID 37194218, 2023). "Some scholars have proposed that YTHDF1 directly targets eIF3C (a subunit of EIF3) and promotes ovarian cancer’s occurrence, metastasis, and prognosis." (PMID 35707365, 2022). "We demonstrated four immune infiltration‐related m6A regulators in ovarian cancer, including RBM15B, ZC3H13, YTHDF1, and IGF2BP1." (PMID 33225598, 2021). "There is evidence that the m6A reader YTHDF1 can enhance the translation of EIF3C and its expression, promoting the malignant progression of ovarian cancer." (PMID 32449290, 2020). "YTHDF1, an m6A Reader, was found to augment EIF3C translation by binding to m6A-modified EIF3C mRNA and to further promote tumorigenesis and metastasis in ovarian cancer." (PMID 32549786, 2020). "Similar to YTHDF1, YTHDF2 plays an oncogenic role in ovarian cancer." (PMID 40483535, 2025). "YTHDF1 enhances EIF3C translation in an m6A-dependent manner by binding to m6A-modified EIF3C mRNA, thereby promoting overall translational output and facilitating ovarian cancer tumorigenesis and metastasis." (PMID 38724996, 2024). "In addition, data from the TCGA database showed the differential expression of tIGF2BP1, YTHDF1 and YTHDF2 genes between normal and ovarian cancer tissues." (PMID 38714753, 2024). "YTHDF1 and YTHDF2 are considered oncogenes in ovarian cancer." (PMID 36999016, 2023). "Mechanistically, YTHDF1 promotes the translation of EIF3C by binding to m6A-modified EIF3C mRNA and concomitantly determines the overall translational output, thereby facilitating tumorigenesis and metastasis of ovarian cancer." (PMID 36650570, 2023). "EIF3C is the direct target of YTHDF1, and increased overall translational output of EIF3C by the regulation of YTHDF1 may facilitate the tumorigenesis and metastasis of ovarian cancer." (PMID 36051357, 2022). "In addition, YTHDF1 was recruited to the m6A modification site of TRIM29, promoting TRIM29 translation in cisplatin-resistant ovarian cancer cells." (PMID 36017491, 2022). "It was reported that m6A reader YTHDF1 bound to m6A-modified EIF3C mRNA and promoted the translation of EIF3C and the overall translational output, consequently facilitating tumorigenesis and metastasis of ovarian cancer." (PMID 36249071, 2022). "Moreover, YTHDF1 can directly target EIF3C and augment EIF3C translation in an m6A-dependent manner, facilitating the tumorigenesis and metastasis of ovarian cancer." (PMID 33758623, 2021).
ovarian carcinoma (continued). "YTHDF1 augmented the translation of EIF3C (HGNC:3279) in an m6A-dependent manner by binding to m6A-modified EIF3C mRNA and concomitantly promoted the overall translational output, thereby facilitating tumorigenesis and metastasis of ovarian cancer." (PMID 35087827, 2021). "As an oncogene, YTHDF1 can affect the overall protein translation in ovarian cancer cells by promoting the translation and overall output of protein translation initiation factor EIF3C mRNA, thus promoting the proliferation, migration, and invasion of ovarian cancer cells." (PMID 38343637, 2024). "In addition, researchers have demonstrated that the m6A reader YTHDF1 acts on EIF3C mRNA, a subunit of the protein translation initiation factor EIF3, to enhance protein translation efficiency in ovarian cancer cells in an m6A-dependent manner, which promotes ovarian carcinogenesis." (PMID 36894952, 2023). "Furthermore, YTHDF1 knockdown inhibited cisplatin-resistant ovarian cancer cells with CSC-like characteristics, suggesting that YTHDF1 is a promising cancer marker to trace the recurrence of ovarian cancer." (PMID 36017491, 2022). "For instance, YTHDF1 can increase the translation of Eukaryotic translation initiation factor 3 subunit C (ELF3C) and promote the overall translation output by combining with the m6A-modified ELF3C mRNA, thus promoting the occurrence and metastasis of ovarian cancer." (PMID 33692959, 2021). "The expression of the m6A RNA methylation regulator in ovarian cancer patients with and without BRCA1 mutation was also analyzed, and it has been found that the expression of both FMR1 and YTHDF1 showed differences between BRCA1-mutation and non-BRCA1-mutation groups (SupportingFigure 5)." (PMID 34187307, 2021). "Study has proved that YTHDF1 might promote the translation of EIF3 via recognizing the m6A-modified sites of EIF3 mRNA and simultaneously augments the overall translational output, thus facilitating tumorigenesis and metastasis in ovarian cancer." (PMID 33015074, 2020). "Importantly, our data showed that immune cell infiltration levels and various immune gene markers were closely associated with the expression of m6A regulators, suggesting that RBM15B, ZC3H13, YTHDF1, and IGF2BP1 might play the role of immune infiltration‐related m6A regulators in ovarian cancer." (PMID 33225598, 2021).
breast cancer (58 papers, 2014 to 2025). A primary or metastatic malignant neoplasm involving the breast. "While researching breast cancer, research has demonstrated that YTHDF1 is a causative factor in cancer, namely in promoting the growth, invasion, and movement of breast cancer cells." (PMID 39821576, 2025). "And we found that high YTHDF1 mRNA expression was associated with a shorter overall survival in breast cancer based on Kaplan–Meier curves and univariate analysis." (PMID 38339157, 2024). "For example, the overexpression of all YTHDF1‐3 has been implicated in breast cancer progression and metastasis." (PMID 38545841, 2024). "The deficiency of YTHDF1 accelerates the growth of breast cancer cells both in vitro and in vivo, suggesting its possible role as an oncogenic factor in breast cancer." (PMID 39342406, 2024). "YTHDF1 amplification is reported to be closely associated with poor overall survival in breast cancer patients." (PMID 36707507, 2023). "In breast cancer, high expression of YTHDF1 and YTHDF3 is associated with gene copy number amplification and induces a poor prognosis." (PMID 36999016, 2023). "The YTHDF1 upregulation is also intrinsically linked with reduced survival time and poor prognosis for breast cancer patients, suggesting the cancer-driving functions of YTHDF1 thereof." (PMID 35319018, 2022). "The finding that YTHDF1 contributes to HR repair and chemoresistance in breast cancer further confirms the association of m6A modification with DNA damage repair." (PMID 35279688, 2022). "Meanwhile, it was found that high YTHDF1 expression was usually associated with reduced survival in patients with breast cancer based on Gene Expression Profiling Interactive Analysis 2 (GEPIA2)." (PMID 35319018, 2022). "Kaplan–Meier analysis of TCGA-BRCA and GSE29272 datasets indicated that increased YTHDF1 was associated with shortened OS, which was a marker of poor prognosis in breast cancer." (PMID 35197112, 2022). "Loss of function studies further showed that YTHDF1 promotes breast cancer cell growth in vitro and in vivo." (PMID 35279688, 2022). "We investigated the specific biological role of YTHDF1 in breast cancer, and our results revealed that YTHDF1 was aberrantly overexpressed and significantly associated with unfavorable survival rates of breast cancer." (PMID 35197112, 2022). "Taken together, these results demonstrate that YTHDF1 was dysregulated in breast cancer and that high expression of YTHDF1 was associated with poor outcomes in patients with breast cancer." (PMID 35197112, 2022). "Whereas overexpression of FOXM1 in breast cancer cells partially counteracted the tumor suppressed effects caused by YTHDF1 silence, which further verified the regulatory relationship between YTHDF1 and FOXM1." (PMID 35197112, 2022). "Among the 986 breast cancer patients, 26.37% samples in high YTHDF1 expression group and 44.62% samples in low expression group occurred genetic mutations, indicating that the frequency of mutations in breast cancer patients was very high." (PMID 34434939, 2021). "To explore underlying molecular mechanisms of YTHDF1 in breast cancer, we screened DEGs between high and low YTHDF1 expression groups." (PMID 34434939, 2021). "Several underlying small molecular compounds against breast cancer were discovered based on YTHDF1-related DEGs." (PMID 34434939, 2021). "The UALCAN online tool was used to analyze the prognostic value of 15 m6A regulators based on medium expression levels from 1,081 breast cancer patients, and just identified that high mRNA expression of YTHDF1 was associated with poor survival (p = 0.0063)." (PMID 34804948, 2021). "Importantly, upregulated YTHDF1 associates with bone metastasis in breast cancer by promoting migration and invasion, inducing osteoclast differentiation, and enhancing Zeste Homolog 2 (EZH2) translation to drive osteolytic progression." (PMID 40986143, 2025).
breast cancer (continued). "The findings showed that YTHDF1 expression was positively linked with the majority of the immunological checkpoints relevant to breast cancer, indicating that YTHDF1 is probably a target for treating breast cancer and determining the effectiveness of therapeutic interventions." (PMID 38339157, 2024). "We propose that YTHDF1 could be used as a prospective biological marker indicating poor prognosis and diagnostic testing in breast cancer." (PMID 38339157, 2024). "Similarly, YTHDF1 is elevated in prostate cancer and breast cancer tissues, and its high expression is associated with nodal metastasis and lymph node metastasis together with poor prognosis respectively." (PMID 36650570, 2023). "Moreover, in breast cancers, YTHDF1 was abnormally expressed compared with normal tissues and higher level of YTHDF1 was closely associated with poor prognosis and immune microenvironment." (PMID 36707507, 2023). "In conclusion, this study confirmed that YTHDF1 is overexpressed in breast cancer and associated with poor prognosis, while hypoxia can promote the expression of YTHDF1 by inducing HIF1α at transcriptional level and inhibiting endogenous miR-16-5p expression at post-transcriptional level." (PMID 35319018, 2022). "Somatic mutations were evaluated in high and low YTHDF1 breast cancer samples from TCGA database." (PMID 34434939, 2021). "For example, in breast cancer research, YTHDF1 recognizes and binds to FOXM1 mRNA through m6A modification, thereby facilitating the translation process of FOXM1 and promoting metastasis." (PMID 39821576, 2025). "A previous study has shown that YTHDF1 facilitates the translation of m6A-modified FOXM1 to enhance breast cancer metastasis." (PMID 40568348, 2025). "The results showed that the expression of YTHDF1 differed with the different immune subtypes of breast cancer (p = 2.2 × 10−14)." (PMID 38339157, 2024). "The findings showed that, in comparison to normal breast tissues, the m6A reading protein YTHDF1 mRNA was considerably increased in breast cancers." (PMID 38339157, 2024). "YTH N6-methyladenosine RNA binding protein 1 (YTHDF1), an m6A reader, has a role in the development and progression of breast cancer as well as the immunological microenvironment." (PMID 38339157, 2024). "YTHDF1 knockdown enhances sensitivity to Adriamycin, cisplatin, and Olaparib in breast cancer cells." (PMID 38545841, 2024). "The mutation frequency of YTHDF1 in breast tumors was 4.7%, with the “amplified” type of CNV being the main type of mutation in the breast cancer cases, occurring at a frequency of alteration of about 4%." (PMID 38339157, 2024). "Breast cancer cells are more susceptible to the PARP inhibitor Olaparib, adriamycin, and cisplatin when YTHDF1 is knocked down, because it facilitates S-phase entrance, DNA replication, and DNA damage repair." (PMID 38339157, 2024). "We then looked into the expression of YTHDF1 in breast cancer tissues and its relationship to prognosis." (PMID 38339157, 2024). "In contrast, most of the other potential targets of miR-660-5p, including VDAC1, TPD52L2, and YTHDF1, play oncogenic roles in breast cancer." (PMID 39709500, 2024). "After that, we analyzed the correlation between YTHDF1 expression in breast cancer and immune stimulatory molecules, immunosuppressive molecules, and MHC molecules, chemokines, and chemokine receptors using the TISIDB database." (PMID 38339157, 2024). "By identifying and binding m6A-modified FOXM1 mRNA and speeding up FOXM1 translation, YTHDF1 aids in the spread of breast cancer." (PMID 39342406, 2024). "YTHDF1 and YTHDF3 are frequently amplified, which is associated with poor prognosis in breast cancer patients." (PMID 38339157, 2024). "YTHDF1 has been proved to promote breast cancer cell growth, DNA damage repair, and chemotherapy resistance." (PMID 39199429, 2024).